CLK1 (CDC like kinase 1)
Description:
Dual specificity kinase acting on both serine/threonine and tyrosine-containing substrates. Phosphorylates serine- and arginine-rich (SR) proteins of the spliceosomal complex and may be a constituent of a network of regulatory mechanisms that enable SR proteins to control RNA splicing. Phosphorylates: SRSF1, SRSF3 and PTPN1. Regulates the alternative splicing of tissue factor (F3) pre-mRNA in endothelial cells.
Synonyms: CLK; CLK/STY; STY
Tractability: Small molecule: a structure with a bound ligand is known; a high-quality ligand is known; it has a high-quality binding pocket; it belongs to a druggable protein family. PROTAC: it is named in the literature on targeted protein degradation; ubiquitination databases record sites on it; its protein half-life has been measured; a small molecule that binds it is known.
Target class: Protein Kinase; Enzyme; CMGC protein kinase group; Kinase; CMGC protein kinase CLK family
Chemical probes: KH-CB19 (high quality), ML197, MU1210 (high quality), PD080979, PD081674, PD082255, PD083666, PD084362, PD084935, PD085238, PD134313, SGC-CLK-1 (high quality), T3-CLK (high quality)
Gene: Protein-coding gene on chromosome 2 (200,853,009 to 200,864,697, reverse strand). Ensembl gene ENSG00000013441.
Subcellular location: Nucleus
Subcellular location (Human Protein Atlas): Nuclear membrane; Nucleoplasm
Gene Ontology:
Molecular function: protein binding; protein serine kinase activity; protein serine/threonine kinase activity; non-membrane spanning protein tyrosine kinase activity; protein tyrosine kinase activity; ATP binding; protein kinase activity; protein serine/threonine/tyrosine kinase activity
Biological process: regulation of RNA splicing
Cellular component: nuclear membrane; nucleoplasm; nucleus
Genetic constraint (gnomAD): Loss-of-function variants: 30 observed, 52.45 expected, observed/expected ratio (o/e) 0.57, 90% interval 0.43 to 0.78. The upper end of that interval is the gene's LOEUF score, 0.78, which puts it in group 3 of 6, group 1 being the genes least tolerant of losing a copy. Missense variants: 487 observed, 541.75 expected, observed/expected ratio (o/e) 0.9, 90% interval 0.83 to 0.97. Synonymous variants: 166 observed, 168.94 expected, observed/expected ratio (o/e) 0.98, 90% interval 0.87 to 1.12.
Homologues: Orthologues: chimpanzee CLK1 (99% identical), macaque CLK1 (98% identical), dog CLK1 (96% identical), rabbit CLK1 (96% identical), pig CLK1 (94% identical), guinea pig CLK1 (91% identical), rat Clk1 (90% identical), mouse Clk1 (89% identical), tropical clawed frog clk1 (69% identical), zebrafish clk4b (57% identical), Drosophila melanogaster mnb (26% identical), Caenorhabditis elegans mbk-1 (23% identical), and 2 more. Paralogues in human: CLK4 (79% identical), CLK2 (54% identical), CLK3 (49% identical), DYRK1B (26% identical), DYRK1A (26% identical), DYRK4 (26% identical), DYRK2 (26% identical), DYRK3 (25% identical), HIPK2 (25% identical), HIPK1 (25% identical), HIPK3 (24% identical), HIPK4 (20% identical).
Diseases named in the same sentence as CLK1 in open-access papers:
CLK1 is named in the same sentence as 77 diseases in open-access papers, as found by Europe PMC text mining. Sharing a sentence is not in itself a finding about the gene and the disease. The quoted sentences say what the papers report.
breast cancer (12 papers, 2010 to 2025). A primary or metastatic malignant neoplasm involving the breast. "CLK1 is known to influence the alternative splicing of genes involved in the cell cycle and is often overexpressed in breast cancer; its pharmacological inhibition can disrupt splicing and hinder tumor growth." (PMID 41017855, 2025). "The increased expression of CLK2 in breast cancer was correlated with the amplification of its locus, whereas the cause of CLK1 upregulation in tumours has not been investigated yet." (PMID 34092037, 2021). "In addition, CLK1 inhibitor TG-003 and inhibitors of SRPKs and CLKs, called Cpd-1, Cpd-2 and Cpd-3, are shown to suppress the proliferation of breast cancer cells." (PMID 32106418, 2020). "CLK1 and FGF22 are oncogenes in cancer and their inhibition leads to the inhibition of breast cancer growth in cell culture and xenograft models." (PMID 34066541, 2021). "Using mass spectrometric analyses, we found that most elevated proteins in Ki8751-treated cancers were all mitochondrial proteins, namely NDFIP1, CLK1, and TEFM, suggesting that Ki8751 treatments may enhance mitochondrial biogenesis of breast cancer cells." (PMID 33628590, 2021). "We confirmed the induction of CLK1, not just in PC3 cells, but also in another prostate cancer cell line, DU145, and in HT29 colorectal and MCF7 breast cancer cell lines." (PMID 29606096, 2018).
glioma (10 papers, 2021 to 2026). A benign or malignant brain and spinal cord tumor that arises from glial cells (astrocytes, oligodendrocytes, ependymal cells). "CLK1 inhibition may prevent chemoresistance in glioma, and CLK1 inhibition by TG693 allows the skipping of mutated exon 31 of the dystrophin gene in Duchenne Muscular Dystrophy." (PMID 34205123, 2021). "Zhanget al. revealed that the overexpression of mitochondrial Clk1 impaired chemoresistance through the AMPK/mTOR/HIF-1α-mediated glycolytic pathway in glioma cells." (PMID 38634120, 2024). "In gliomas, the expression of DYRK3 and CLK3 correlated with worse survival, while DYRK1A, DYRK2 and CLK1 were associated with better disease outcomes." (PMID 38398225, 2024). "Analysis of TCGA data showed high induction of Clk1 in gliomas or renal tumors, whereas in bladder urothelial carcinomas and invasive breast cancers, Clk1 expression was decreased." (PMID 35463320, 2022). "Furthermore, knockdown of CLK1 In glioma cells (GL261) increased aerobic glycolysis and expression of HIF-1α via the AMPK/mTOR signaling pathway." (PMID 39742274, 2024). "Studies have found that downregulating the CLK1 gene in glioma GL261 cells can inhibit mitochondrial function, reduce AMPK phosphorylation levels, activate the mTOR signaling pathway, promote the upregulation of HIF-1α in tumor cells, and enhance the sensitivity of GL261 cells to chemotherapy drugs." (PMID 34568328, 2021). "Previously, CLK1 could modulate the chemoresistance of glioma cells via glycolytic signaling mediated by AMPK/mTOR/HIF-1α as well as participating in modulating the splicing process of gastric cancer, serving as an underlying therapeutic target against this malignancy." (PMID 35832557, 2022). "n gliomas, SRSF11 modulates the splicing of CDC-like kinase 1 (CLK1), a cell cycle-related splicing factor, by promoting exon 4 inclusion that increases protein expression and activity." (PMID 41584036, 2026). "S5B), analysis of the GlioVis Chinese Glioma Genome Atlas (CGGA) dataset shows a significant association of higher expression of CLK2, but not CLK1, CLK3, or CLK4, with poor OS, and CLK2 mRNA expression significantly increases with grade in multiple brain cancers, including GBM." (PMID 35731869, 2022).
Duchenne muscular dystrophy (7 papers, 2017 to 2022). Duchenne muscular dystrophy (DMD) is a neuromuscular disease characterized by rapidly progressive muscle weakness and wasting due to degeneration of skeletal, smooth and cardiac muscle. "Our findings support further exploration of pharmacologic inhibition of CLK1 as a potential new treatment for obesity associated diabetes, beyond oncology, Duchenne muscular dystrophy and Alzheimer’s disease." (PMID 34526909, 2021). "Additionally, pharmacological inhibition of CLK1 has been investigated pre-clinically for the treatment of Duchenne muscular dystrophy and Alzheimer’s disease." (PMID 34526909, 2021). "The CLK1 inhibitor, TG693, is a splicing modulator with therapeutic potential for patients with Duchenne muscular dystrophy." (PMID 35565529, 2022).
gastric cancer (7 papers, 2022 to 2024). A primary or metastatic malignant neoplasm involving the stomach. "Among the other interesting candidates, the CLK1 gene is highly expressed in normal breast tissue, according to the human protein atlas, and has also been linked to the regulation of mRNA-splicing processes in gastric cancer." (PMID 35625741, 2022). "Experiments using patient-derived tumor samples have shown that CLK1 is a potential target for gastric cancer treatment." (PMID 39742274, 2024). "CLK1 plays a crucial role in the regulation of proliferation, invasion and migration in gastric cancer and was described as a novel therapeutic target." (PMID 38033043, 2023). "Similarly, inhibition of Clk1 using TG003 and Clk1 siRNA resulted in a decreased cell viability, proliferation, invasion and migration as well as modulation in the phosphorylation of SRSF2, which validated the use of Clk1 as a potential target for gastric cancer treatment." (PMID 37658940, 2023).
influenza (7 papers, 2015 to 2025). An acute viral infection of the respiratory tract, occurring in isolated cases, in epidemics, or in pandemics; it is caused by serologically different strains of viruses (influenzaviruses) designated A, B, and C, has a 3-day incubation period, and usually lasts for 3 to 10 days. "Cdc2-like kinase 1 (CLK1) has been recognized as a potential anti-influenza target owing to alternative splicing of the M1 gene in influenza viruses." (PMID 40539108, 2025). "siRNA screens have shown that influenza is sensitive to shifts in splice factor function as depletion of CLK1, a kinase that phosphorylates SR proteins, or treatment with the CLK inhibitor TG003, results in loss of virus replication." (PMID 39861843, 2024). "It was demonstrated that gallocatechin-7-gallate isolated from Pithecellobium clypearia is an inhibitor of host cdc2-like kinase 1 (CLK1), an anti-influenza target due to its role in viral M2 mRNA alternative splicing." (PMID 34202374, 2021). "There is interest in the potential of targeting CLK1 in the context of the influenza and HIV-1 viruses and in cancer cells." (PMID 29606096, 2018). "Cdc2-like kinase 1 (CLK1) in the host cells is responsible for alternative splicing of the M2 gene of influenza virus during influenza infection and replication." (PMID 26540031, 2015). "CPE reduction assay was conducted to evaluate the anti-influenza ability of CLK1 inhibitors with three different drug administrations: simultaneous treatment assay, pre-treatment assay and post-treatment assay in MDCK cell." (PMID 26540031, 2015). "Host cdc2-like kinase 1 (CLK1) has a key role in the splicing of the H1N1 influenza virus M2 gene and is an important anti-influenza target." (PMID 34202374, 2021). "CLK1 is vital in splicing the H1N1 influenza virus M2 gene and is a critical anti-influenza target." (PMID 35983093, 2022).
prostate carcinoma (7 papers, 2009 to 2025). A carcinoma that arises from epithelial cells of the prostate gland. "The splice factor and splice factor kinase antiapoptotic isoform CLK1 can be induced by hypoxia to produce the antiapoptotic isoform caspase 9b in prostate cancer cells, which may be involved in antitumor therapy resistance." (PMID 34692669, 2021). "Here we have targeted CLKs in prostate cancer cells with the benzothiazole TG003, a well-established small molecule inhibitor of CLK1 and CLK431." (PMID 33846420, 2021).
ovarian carcinoma (5 papers, 2010 to 2026). A malignant neoplasm originating from the surface ovarian epithelium. "Our findings reveal a novel mechanism underlying PARPi sensitivity and suggest that targeting CLK1 in combination with PARPi may represent a promising therapeutic strategy for PARPi-resistant ovarian cancer." (PMID 41191919, 2026). "Based on the screening and validated through further experiments, we confirmed that CLK1 knockdown is synthetically lethal with PARPi in ovarian cancer." (PMID 41191919, 2026). "CLK1, a member of the CLKs family that phosphorylates SR proteins involved in splicing, was shown to promote the phosphorylation of SPF45 when overexpressed, which ultimately induces cell migration and invasion of ovarian cancer." (PMID 32793288, 2020).
Alzheimer disease (4 papers, 2021 to 2026). A progressive, neurodegenerative disease characterized by loss of function and death of nerve cells in several areas of the brain leading to loss of cognitive function such as memory and language. "By comparing the differential gene expression profile of Sin1 treated cells to cells incubated with ladostigil before being exposed to Sin1, we observed an over-expression of Clk1 (Cdc2-like kinase 1) which was implicated in psychophysiological stress in mice and Alzheimer’s disease." (PMID 34572436, 2021).
colorectal cancer (4 papers, 2018 to 2024). A primary or metastatic malignant neoplasm that affects the colon or rectum. "Upregulated expression of CLK1 and CLK2 is negatively correlated with prognosis in patients with kidney tumors and glioblastoma/colorectal carcinoma, respectively." (PMID 37342192, 2023). "While our model highlights a molecular scenario that explains how homeostasis of SR protein phosphorylation may be achieved through CLK1 splicing regulation, it is important to note that our study has been limited to the HCT116 colorectal cancer cell line." (PMID 39251328, 2024). "CLK1 and CLK2 are upregulated in breast and colorectal carcinomas and glioblastoma." (PMID 37342192, 2023).
pancreatic cancer (4 papers, 2021 to 2026). "To explore the underlying mechanism of CLK1 in pancreatic cancer progression, we firstly determined the overall impact of differentiated CLK1 expressions on whole gene expression levels." (PMID 33849617, 2021). "Thus, our results suggest that CLK1-mediated phosphorylation of SRSF5 on Ser250 is a potential mechanism underlying the pro-oncogenic functions of CLK1 in pancreatic cancer." (PMID 33849617, 2021). "The results showed that when CLK1 was at a high expression level, pancreatic cancer patients with high expression levels of SRSF5 have a poorer prognosis than those with low SRSF5 expression levels." (PMID 33849617, 2021). "Collectively, our results indicated that CLK1 acted as an oncogenic factor through promoting the proliferation of pancreatic cancer cells both in vitro and in vivo." (PMID 33849617, 2021). "To further evaluate the relationship between expression of CLK1 and clinicopathological features in pancreatic cancer, we determined CLK1 protein expression in paraffin-embedded pancreatic cancer specimens from 186 patients using IHC." (PMID 33849617, 2021). "Similar patterns were observed in CCK-8 and cell counts assays, suggesting the proliferative role of CLK1 in human pancreatic cancer progression in vitro." (PMID 33849617, 2021). "Next, we evaluated the effect of manipulated CLK1 expressions on pancreatic cancer cell growth in vivo." (PMID 33849617, 2021). "Taken together, these results suggest that elevated CLK1 expression in pancreatic cancer correlated with worse prognosis of PDAC patients." (PMID 33849617, 2021). "In addition, inhibited exon skipping of METTL14 and enhanced exon skipping of Cyclin L2 caused by CLK1’s enhancing SRSF5 SRSF5250-Ser phosphorylation enhanced the N6-methyladenosine modification level and cancer aggressiveness in pancreatic cancer." (PMID 36977668, 2023). "Therefore, our results indicated that CLK1 expression promoted the metastatic ability of human pancreatic cancer cells in vitro and in vivo." (PMID 33849617, 2021). "In addition, further quantitation of CLK1 mRNA and protein revealed that pancreatic cancer tissues had higher levels of CLK1 expression than the adjacent non-tumor tissues." (PMID 33849617, 2021). "Moreover, compared to the normal human pancreatic duct epithelial (HPDE) cells, human pancreatic cancer cell lines including PANC-1, 8988, Aspc-1, SW1990, BxPC-3 had more CLK1 protein expression." (PMID 33849617, 2021).
colon adenocarcinoma (3 papers, 2020 to 2023). "Mutations of SKIDA1, CLK1, NSFL1C, OR2A5, EDEM3, and OR51V1 were associated with significant deregulation of DDX20 gene expression pattern in colon adenocarcinoma patients." (PMID 36011315, 2022).
lung carcinoma (3 papers, 2010 to 2024). "The kinase screening also revealed a low remaining activity for CLK1 and CLK4, to our best knowledge, two kinases which have not been linked to lung cancer." (PMID 33435251, 2021).
osteosarcoma (3 papers, 2023 to 2025). A usually aggressive malignant bone-forming mesenchymal neoplasm, predominantly affecting adolescents and young adults. "Based on network pharmacology and transcriptomics, we identified ATP1A1, CLK1, SIGMAR1, PYGM, and HSP90B1 as the key targets of solasonine that influence the progression of osteosarcoma cells." (PMID 40831924, 2025). "In this study, five possible key targets of SS against osteosarcoma were finally identified: ATP1A1, CLK1, SIGMAR1, PYGM, and HSP90B1." (PMID 40831924, 2025). "It is speculated that ATP1A1, CLK1, SIGMAR1, PYGM, and HSP90B1 may serve as therapeutic targets for solasonine in the treatment of osteosarcoma." (PMID 40831924, 2025).
viral infection (3 papers, 2014 to 2024). "By contrast, our screen did replicate previous studies that found CLK1 and RAB11FIP3 to influence viral infection." (PMID 33269701, 2020). "In addition, a HTS RNAi study using pandemic swine-origin influenza virus identified 168 factors that inhibit virus infection, including the SON DNA binding protein (SON) that controls the trafficking of virions to late endosomes, as well as CDC-like kinase 1 (CLK1)." (PMID 24952721, 2014). "Notably, the viral infection also led to marked changes in the expression of select SR kinases, though the specific kinase affected varied between the viruses and cell lines: influenza PR8 infection of A549 cells reducing CLK1 levels while HCoV-229E infection of Huh7 cells decreased CLK3 abundance." (PMID 39861843, 2024).
brain tumors (2 papers, 2025 to 2026). "Next, we searched all DepMap profiled cell lines and found that the pediatric brain tumor cell line KNS-42 had a strong dependency on CLK1 (low CRISPR dependency score) and chose it for further in vitro testing." (PMID 39149264, 2025). "Altogether, these data suggest that CLK1 Exon 4-containing transcripts are upregulated in pediatric brain tumors compared to cell type controls and adult normal tissues." (PMID 39149264, 2025). "We selected KNS-42 along with two additional cell lines from our pediatric brain tumor cohort with high CLK1 exon 4 PSI (7316–1763 and 7316–1769) to experimentally validate the exon 4 splice event identified from short-read RNA-Seq." (PMID 39149264, 2025). "Indeed, we observed widespread high median CLK1 exon 4 inclusion levels across pediatric brain tumors, suggesting these tumors contain active CLK1." (PMID 39149264, 2025). "Importantly, we found that overall pediatric brain tumors had higher proportions of CLK1 exon 4 containing transcripts than in adult brain region tissues, but similar levels to those in Evo-Devo, suggesting this may be an oncofetal transcript." (PMID 39149264, 2025).
diabetes (2 papers, 2019 to 2021). "In this study, we defined inhibition of CLK1 as a potential strategy to induce WAT browning and prevent obesity and associated diabetes as an alternative to cold exposure." (PMID 34526909, 2021).
glioblastoma (2 papers, 2021 to 2023). The most malignant astrocytic tumor (WHO grade IV). "Moreover, high expression levels of CLK1 or CLK2 were associated with negative prognosis in renal carcinoma and glioblastoma, respectively." (PMID 34092037, 2021).
pancreatic ductal adenocarcinoma (2 papers, 2021 to 2023). An infiltrating adenocarcinoma that arises from the epithelial cells of the pancreas. "RNA sequencing (RNA-seq) was performed using 15 pairs of pancreatic ductal adenocarcinoma (PDAC) tissues and corresponding normal tissues, and Cdc2-like kinases 1 (CLK1) was identified as a significantly upregulated alternative splicing related gene." (PMID 33849617, 2021).
breast tumor (1 paper, 2025). "Interestingly, CLK1 and CLK4 mRNA expression levels were significantly lower in breast tumor-to-normal and TNBC-to-ER positive comparisons." (PMID 40731028, 2025).